SMKR1 (small lysine rich protein 1)
Tractability: No criterion of Open Targets' tractability assessment is met for any kind of drug.
Gene: Protein-coding gene on chromosome 7 (129,502,531 to 129,512,918, forward strand). Ensembl gene ENSG00000240204.
Subcellular location (Human Protein Atlas): Nucleoli
Genetic constraint (gnomAD): Loss-of-function variants: 5 observed, 5.73 expected, observed/expected ratio (o/e) 0.87, 90% interval 0.45 to 1.7. That is too few expected variants to judge how well the gene tolerates losing a copy. Missense variants: 56 observed, 83.93 expected, observed/expected ratio (o/e) 0.67, 90% interval 0.54 to 0.83. Synonymous variants: 38 observed, 33.17 expected, observed/expected ratio (o/e) 1.15, 90% interval 0.88 to 1.5.
Homologues: Orthologues: macaque SMKR1 (100% identical), chimpanzee SMKR1 (98% identical), dog SMKR1 (85% identical), rabbit SMKR1 (83% identical), rat Smkr1 (78% identical), pig SMKR1 (77% identical), zebrafish smkr1 (52% identical).
Diseases named in the same sentence as SMKR1 in open-access papers:
SMKR1 is named in the same sentence as 1 disease in open-access papers, as found by Europe PMC text mining. Sharing a sentence is not in itself a finding about the gene and the disease. The quoted sentences say what the papers report.
cancer (1 paper, 2024). A tumor composed of atypical neoplastic, often pleomorphic cells that invade other tissues. "While the downregulated gene OSGEP is associated with tRNA modification, and its mutations can lead to various neurological abnormalities, SMKR1 is involved in the process of cancer occurrence, which is closely related to cancer recurrence." (PMID 38891594, 2024).